ZNF510 (zinc finger protein 510)
Description:
May be involved in transcriptional regulation.
Synonyms: KIAA0972
Tractability: Antibody: the Human Protein Atlas places it where antibodies can reach.
Gene: Protein-coding gene on chromosome 9 (96,754,553 to 96,778,129, reverse strand). Ensembl gene ENSG00000081386.
Subcellular location: Nucleus
Subcellular location (Human Protein Atlas): Nucleoplasm; Plasma membrane; Vesicles
Pathways (Reactome):
Gene expression (Transcription): Generic Transcription Pathway
Gene Ontology:
Molecular function: DNA-binding transcription factor activity, RNA polymerase II-specific
Biological process: regulation of transcription by RNA polymerase II; regulation of DNA-templated transcription
Cellular component: nucleus
Genetic constraint (gnomAD): Loss-of-function variants: 15 observed, 19.44 expected, observed/expected ratio (o/e) 0.77, 90% interval 0.51 to 1.19. The upper end of that interval is the gene's LOEUF score, 1.19, which puts it in group 5 of 6, group 1 being the genes least tolerant of losing a copy. Missense variants: 724 observed, 828.89 expected, observed/expected ratio (o/e) 0.87, 90% interval 0.82 to 0.93. Synonymous variants: 261 observed, 279.86 expected, observed/expected ratio (o/e) 0.93, 90% interval 0.84 to 1.03.
Homologues: Orthologues: chimpanzee ZNF510 (98% identical), macaque ZNF510 (90% identical), dog ZNF510 (73% identical), pig ZNF510 (73% identical), mouse Zfp819 (31% identical). Paralogues in human: ZNF33B (40% identical), ZNF33A (40% identical), ZNF658 (38% identical), ZNF841 (37% identical), ZNF37A (37% identical), ZNF585B (36% identical), ZNF717 (36% identical), ZNF182 (35% identical), ZNF836 (35% identical), ZNF484 (35% identical), ZNF334 (35% identical), ZNF606 (35% identical), and 164 more.